IRAK3 (interleukin 1 receptor associated kinase 3)
Diseases named in the same sentence as IRAK3 in open-access papers (continued):
Sharing a sentence is not in itself a finding about the gene and the disease.
tumor (31 papers, 2009 to 2025). "Accumulating evidence supports that IRAK3 expression in tumor-associated macrophages impairs cancer cell immune surveillance while effectively preventing excessive inflammation that drives cancer progression." (PMID 40755754, 2025). "Enhancing the host immune response in IRAK3-deficient mice can inhibit the growth of transplanted cancer cells, highlighting the critical role of IRAK3 in tumor immune regulation." (PMID 40755754, 2025). "Our preclinical observations are confirmed in a patient data set with urothelial cancers, where the expression of IRAK3 mRNA in pretreatment tumor tissues is associated with the inflammatory signatures and the treatment outcome of ICB therapy." (PMID 36757800, 2023). "Using a range of carcinogen-induced or oncogene-driven murine tumor models, our data show that IRAK3 deficiency resulted in enhanced activation of myeloid cells in tumor tissues, which could improve the migratory and antigen-presentation capacity of the cells." (PMID 36757800, 2023). "Furthermore, IRAK3 is an important regulator by which tumor-associated macrophages mimic the phenotype of alternatively activated (M2) macrophages." (PMID 23620818, 2013). "Tumors with low IRAK3 levels showed a significant enrichment of M1-like macrophages, T follicular helper cells, activated CD4+ memory T cells, and memory B cells, whereas monocytes and mast cells were more abundant in IRAK3-high tumor samples." (PMID 38334625, 2024). "Of note, removal of IRAK3 in mice resulted in significantly delayed tumor growth in both models and substantially increased the proportion of small tumors at the study endpoint." (PMID 36757800, 2023). "Because IRAK3 deletion was in the germline in our model, we tested the lineage-specific effects on tumor growth using a myeloid cell depletion antibody against murine CSF-1R." (PMID 36757800, 2023). "Genetic deletion of IRAK3 in immunocompetent mice enables efficient tumor growth inhibition and synergizes with ICB treatment." (PMID 36757800, 2023). "Consistent with earlier results, germline deletion of IRAK3 resulted in delayed tumor growth in mice treated with the isotype control antibody." (PMID 36757800, 2023). "A total of 80% of IRAK3-KO mice receiving a PD-1 blocking antibody showed small tumors (< 200 mm3) at day 40 after tumor implantation, compared with 16% of anti-PD-1–treated WT mice." (PMID 36757800, 2023). "Further, our findings in this study provide insights into immunosuppressive mechanisms in the tumor microenvironment, where IRAK3 serves as a key regulator for signal transduction, antigen presentation, inflammatory response, and response to ICB therapy." (PMID 36757800, 2023). "The results exhibited that tumor volume and weight were restrained in the sh-circ_IRAK3 group in contrast to the sh-NC group." (PMID 35164763, 2022). "Functional experiments presented that circ_IRAK3 silencing induced BC cell apoptosis, curbed cell proliferation, migration, and invasion in vitro, and decreased tumor growth in vivo." (PMID 35164763, 2022). "We also observed that the levels of KIF2A mRNA and protein were apparently decreased in mice tumor tissues of the sh-circ_IRAK3 group." (PMID 35164763, 2022). "Overall, IRAK3 activation leads to immunosuppression and allows the communication between tumor cells and macrophages facilitating cancer progression and a favorable microenvironment for the tumor." (PMID 29617451, 2018). "The evaluation of IRAK3 PROTAC degraders in vivo in preclinical models may pave the way for a new generation of checkpoint inhibitors for different tumor types, especially for cold tumors showing a poor T and B cell infiltrate." (PMID 38334625, 2024). "These two cell populations showed a strong correlation in IRAK3-KO tumor–bearing mice." (PMID 36757800, 2023). "Moreover, activation of dendritic cells and frequency of CD38+ cytotoxic T cells in tumor tissues were significantly elevated by the PD-1 blockade in IRAK3-KO mice." (PMID 36757800, 2023).
tumor (continued). "Moreover, a subset of CD8+ T cells that coexpress PD-1 and CD38 was only found in tumor tissues and was significantly upregulated as a result of IRAK3 deletion." (PMID 36757800, 2023). "40% of anti-PD-1 treated control mice or 60% of the isotype-treated IRAK3-KO mice were tumor free." (PMID 36757800, 2023). "Also, circ_IRAK3 inhibition reduced tumor growth in vivo and induced cell cycle arrest, apoptosis, impeded colony formation, proliferation, migration, and invasion of BC cells in vitro." (PMID 35164763, 2022). "Moreover, the expression of circ_IRAK3 was markedly reduced in mice tumor tissues of the sh-circ_IRAK3 group compared to the control group, while the expression of miR-603 was overtly increased." (PMID 35164763, 2022). "Interleukin-1 receptor-associated kinase 3 (IRAK3) is the major pathway involved in recurrence in younger patients, while Wnt10b-related genes is the major pathway associated with recurrence in older patients with tumor-positive SLNs." (PMID 33373316, 2020). "The upregulation of the gene IRAK3 may provide a clue about the mechanisms leading to immune evasion by tumor cells." (PMID 29617451, 2018). "Furthermore, analysis of the GSE13507 dataset revealed that six genes, LIMS2, IRAK3, STX2, CYP27A1, IL11RA, and KCNMB1, had AUC values greater than 0.7, demonstrating good diagnostic potential in differentiating healthy adjacent tissues from tumor samples." (PMID 40755754, 2025). "In order to assess tumor-driven immunological changes using flow cytometry, we selected EO771 tumors that showed comparable growth rates in WT and IRAK3-KO mice." (PMID 36757800, 2023). "The strong correlation between the expression levels of RAB31, IRAK3, and OBSCN and the gene expression profile suggestive of CAF infiltrations strongly supported the tumor-promoting role of these genes in the hub cancers." (PMID 34359748, 2021). "The prioritization of the hub genes in the gene expression profiles suggestive of tumor immune evasion and immunotherapy response occurs in the order of RAB31 > TNPO2 > OBSCN > IRAK3 > LIN9 > SEC16B." (PMID 34359748, 2021). "Furthermore, qRT-PCR experiments showed that LIMS2, IRAK3, STX2, IL11RA, KCNMB1, and PDLM7 were significantly downregulated in the tumor group, consistent with the bioinformatic analysis results, suggesting their potential clinical value." (PMID 40755754, 2025). "Notably, RAB31, IRAK3, OBSCN, LIN9, TNPO2, and SEC16B expressions were inversely correlated with the gene expression profiles suggestive of tumor purity of the hub cancer." (PMID 34359748, 2021). "To validate the expression levels of the eight key genes (LIMS2, TP53INP2, IRAK3, STX2, CYP27A1, IL11RA, KCNMB1, and PDLIM7) in tumor and non-tumor samples, we analyzed their expression in TCGA and GSE7476 datasets." (PMID 40755754, 2025). "Among the cell populations that were not impacted by the tumor volume, we observed significant enrichment of activated dendritic cells and macrophages (CD86+MHCII+) in tumors from IRAK3-KO mice." (PMID 36757800, 2023). "Interestingly, we found that IRAK genes were all positively correlated with DNAss in LGG, although not significant for IRAK3, suggesting that IRAK family genes tend to facilitate tumor stemness in LGG." (PMID 35211171, 2022).
infection (26 papers, 2009 to 2025). The state of being infected such as from the introduction of a foreign agent such as serum, vaccine, antigenic substance or organism. "In the context of infection and inflammation, IRAK3 prevents immune overreaction by negatively regulating the TLR signaling pathway, thus safeguarding host tissues from damage." (PMID 40918148, 2025). "The genes IKBKB, IRAK3, IRF5, MAP2K4 (MEK4), MAPK14 (p38), MAPK8 (JNK1) and NFKB1 (p50) were upregulated not only in both cell types, but also after infection with whole bacteria of P. gingivalis W83 as well as with the membrane fraction." (PMID 28056810, 2017). "IRAK3, BIRC3 and TNF were dysregulated throughout the entire infection and were classified into the apoptosis pathway." (PMID 21629653, 2011). "We identified 6 hub genes (IL1R1, CD163, TLR5, LY96, MMP9, and IRAK3) and 4 target miRNAs (miR-34a-5p, miR-103-3p, miR-107, and miR-124-3p) that affect the pathophysiological processes of T2DM and CS through ion transport, immune response, and infection." (PMID 40922361, 2025). "MRNA levels of genes encoding for chemokines (CXCL1 and CXCL5), cytokines (IL-10, IL-15 and IL-32), pattern recognition receptors (TLR1) and innate signaling molecules like IRAK3 and TRAF6, were all increased after MVA-C infection in comparison with MVA-WT-infected cells." (PMID 22536391, 2012). "The interleukin-1-receptor-associated kinase 3 (IRAK3) was identified as a negative feedback regulator of inflammatory events and hence as a relevant factor for properly calibrating the immune response against infections." (PMID 31616422, 2019). "The main findings of this study were the observations that high VT MV, in the absence of infection, induced up-regulation of TLR4 and down-regulation of IRAK3 and IκBα protein levels, resulting in an increase of pro-inflammatory cytokines levels in the lungs and in the systemic circulation." (PMID 20199666, 2010).
cancer (24 papers, 2009 to 2025). A tumor composed of atypical neoplastic, often pleomorphic cells that invade other tissues. "In IRAK3-KO mice, IRAK3 deficiency delayed the growth of various murine cancer cell lines, and ICB treatment induced superior growth inhibition compared to wild-type mice." (PMID 38334625, 2024). "IRAK3 deficiency delayed the growth of carcinogen-induced and oncogene-driven murine cancer cells and induced enhanced activation in myeloid cells and T cells." (PMID 36757800, 2023). "Additionally, certain SNPs of the human IRAK3 gene are associated with the risk of cancer." (PMID 31616422, 2019). "Altogether, our study demonstrated what we believe to be a novel cancer-driven immune tolerance program controlled by IRAK3 in humans and mice and proposed its suitability as an immunotherapy target." (PMID 36757800, 2023). "IRAK3 has recently been studied for targeting to enhance pro-inflammatory cytokine signaling in cancer." (PMID 37509311, 2023). "Although the biology of IRAK3 has been reported in experimental models, there is scarce evidence to show its clinical relevance and therapeutic potential in cancer immunotherapy." (PMID 36757800, 2023). "Modulating cGMP signaling limits cancer cell proliferation and survival, and IRAK3 contributes to the progression of both inflammation and cancer, likely via modulation of NFκB signaling, which provides a critical link between both conditions." (PMID 37239919, 2023). "IRAK2 and IRAK4 were moderately expressed, and IRAK3 expression was the relatively lowest in pan-cancer." (PMID 35211171, 2022). "Further studies are needed to explore the prognostic value of IRAK3 in other cancers." (PMID 38334625, 2024). "Induction of IRAK3 expression is required for development of ‘endotoxin tolerance’ and ‘cancer-induced monocyte tolerance’, and tumors with high IRAK3 expression show enriched anti-inflammatory pathways and a worse clinical response to immune checkpoint blockade therapy." (PMID 37239919, 2023). "In humans, published results suggest that cancer-derived factors could constrain the activation of human myeloid cells by enhancing IRAK3 expression." (PMID 36757800, 2023). "The mRNA expression levels of OBSCN and IRAK3 were associated with resistance to vemurafenib, while the IC50 concentrations of other drugs correlate negatively with the expression levels of the hub genes in the cancer cell lines." (PMID 34359748, 2021). "However, further studies are needed to explore the prognostic value of IRAK3 in other cancer types." (PMID 36757800, 2023). "Specifically, single nucleotide variation (SNV) of OBSCN is the most frequently predicted gene alteration, while SNV of SEC16B, IRAK3, TNPO2, LIN9, and RAB31 constituted 9%, 5%, 5%, 4%, and 2% of genetic alterations in the TCGA cohort of the hub cancers." (PMID 34359748, 2021). "The high expression levels of RAB31, IRAK3, and TNPO2 were strongly correlated with gene expression profiles suggestive of dysfunctional T cell phenotypes in the six cancers." (PMID 34359748, 2021). "We found that in all the six cancer types analyzed, the expression levels of RAB31 and IRAK3 were positively correlated (all p-value < 0.05) with the gene expression profiles suggestive of infiltrations of all immune cell types analyzed (except B cells)." (PMID 34359748, 2021). "Our analysis revealed that IRAK3 mRNA was absent in cancer cells and nonmyeloid immune cells but was found in fibroblasts and endothelial cells." (PMID 36757800, 2023). "Although our study revealed clinical and mechanistic insights of IRAK3 as a drug target in synergy with ICB therapy, further hypotheses could be explored to uncover the link between IRAK3 and the microbiome, immunogenic cell death, and cancer metastasis." (PMID 36757800, 2023). "Also, IRAK2, IRAK3, and IRAK4 were higher expressed in the C6 subtype in pan-cancer." (PMID 35211171, 2022).
cancer (continued). "Similarly, we queried the survival differences between the mRNA expression levels of each hub gene across the combined cohorts of the hub cancers and found that higher mRNA expression levels of RAB31, IRAK3, SEC16B, and LIN9 predicted shorter survival durations of the hub cancer cohorts." (PMID 34359748, 2021). "Similarly, the expression levels of RAB31, IRAK3, and SEC16B were inversely correlated, while TNPO2 and LIN9 were positively correlated with gene expression profiles suggestive of MDSCs infiltration in the six cancer types." (PMID 34359748, 2021). "Interestingly, the low rather than high levels of CSNK1E, IGF2R, IRAK3, and PRKAA1 relate to poor cancer prognosis, suggesting that kinases often play a divergent role in different types of cancer." (PMID 26956052, 2016). "In addition, several of these genes have not previously been reported as methylated in any type of cancer (KCNK4, SEPT5, PENK, BMP4, TAL1, PGF, SMARCB1 (INI1), FRZB (SFRP3), IRAK3 and MCM2)." (PMID 19493342, 2009).
bacterial infection (6 papers, 2012 to 2023). "A previous study suggested that IRAK3 is a negative signal regulator, and a higher inflammatory response to bacterial infection and increased susceptibility to LPS-induced septic shock are observed in IRAK3−/− mice." (PMID 36611753, 2022). "Several lines of evidence suggest that IRAK3 is a negative regulator of signaling, since there is an enhanced inflammatory response to bacterial infection and increased susceptibility to LPS-induced septic shock in IRAK3−/− mice." (PMID 33238146, 2021). "LNC_001066 and LNC_000231 co-regulated the expressions of immune-related target genes, IRAK3 and TLR8, to participate in the progress of host immune response in defensing bacterial infection through apoptosis and toll-like receptor signaling pathway, respectively." (PMID 30760749, 2019).
cardiovascular disease (2 papers, 2012 to 2023). "Indeed, in recent studies higher adiponectin was associated with a significant increase in cardiovascular disease mortality in patients with metabolic diseases, and suggest that patients with low IRAK3 may not benefit from treatment with adiponectin or adiponectin mimetics." (PMID 22272346, 2012).
metabolic disease (2 papers, 2012 to 2022). A congenital disorder (due to inherited enzyme abnormality) or acquired (due to failure of a metabolically important organ) disorder resulting from an abnormal metabolic process. "Circulating ox-LDL levels, also associated with metabolic disorders, were increased in obese patients, remained high after weight loss and correlated negatively with IRAK3 expression in monocytes (rs = −0.32, P<0.05)." (PMID 22272346, 2012).
central nervous system diseases (1 paper, 2024). "In other words, IRAK3 could be considered a promising new therapeutic target for central nervous system diseases." (PMID 39346771, 2024).
IRAK3 also shares sentences with these, for which no sentence is quoted: acute myocardial infarction (4 papers); infectious disease (3); inflammation (3); viral infection (3); infarction (2); Insulin resistance (2); prostate carcinoma (2); alcoholic liver damage (1); allergic asthma (1); ankylosing spondylitis (1); bacterial pneumonia (1); bladder tumor (1); bone sarcoma (1); brain disorder (1); breast tumors (1); cardioembolic stroke (1); cardiomyopathy (1); cerebral infarct (1); childhood asthma (1); cholangiocarcinoma (1); chronic lymphocytic leukemia (1); edema (1); familial hypercholesterolemia (1); fibrosarcoma (1); gastritis (1); glioma (1); graft-vs.-host disease (1); Graves disease (1); Hyperglycemia (1); Hypertension (1).
A further 21 diseases each share a sentence with IRAK3 in 1 paper.